EGFR (epidermal growth factor receptor)
Diseases named in the same sentence as EGFR in open-access papers (continued):
Sharing a sentence is not in itself a finding about the gene and the disease.
lung cancer (continued). "According to the literature, patients with epidermal growth factor receptor mutation-positive lung cancer tend to have a good prognosis following treatment with targeted therapy." (PMID 25621024, 2015). "Up to 20% of EGFR-mutated lung cancers that have developed acquired resistance to TKIs also exhibit MET amplification in this setting." (PMID 26517520, 2015). "TKIs with activities against EGFR are effective in lung cancer patients with EGFR mutations; however, resistance emerges over time." (PMID 25955608, 2015). "Epidermal growth factor receptor (EGFR) gene mutations occur in 10% to 50% of stage IV nonsmall cell lung cancer." (PMID 26496308, 2015). "The use of targeted therapies have led to an increase in survival of lung cancer patients with certain genetic alterations such as epidermal growth factor receptor (EGFR) activating mutations and anaplastic lymphoma kinase (ALK) rearrangements." (PMID 26603430, 2015). "SCLC transformation is a relatively rare acquired resistance mechanism in lung cancers with EGFR gene mutation." (PMID 26400668, 2015). "We also analyzed lung cancer patients with single or complex EGFR exon 18 mutations and their correlation to treatment outcome with EGFR-TKI." (PMID 26354324, 2015). "Studies have shown that EGFR with a T790M mutation, a secondary mutation in the EGFR kinase domain, is highly correlated with lung cancer relapse." (PMID 26312766, 2015). "The 1st generation reversible EGFR-TKIs, gefitinib and erlotinib, dramatically changed the treatment strategy for patients harboring EGFR mutated lung cancer." (PMID 26515464, 2015). "Currently, except for recent developments in relation to the involvement of EGFR mutational status, limited advances in the detection of molecular targets in lung cancer were obtained." (PMID 26250468, 2015). "EGFR mutation rates as well as clinical and pathological manifestations between P-LC and control lung cancer patients were compared." (PMID 25715252, 2015). "We evaluated this method using a cell mixture composed of various ratios of lung cancer cells harboring mutated or wild-type EGFR, lung cancer tissues obtained by surgery, and a cytology sample obtained by bronchoscopy from a lung cancer patient." (PMID 25591975, 2015). "EGFR is expressed at high levels in a wide range of tumor types and in most lung cancers it has been associated with lower rates of survival." (PMID 25674792, 2015). "KRAS is a frequently mutated oncogene in lung cancer and among the most refractory to EGFR targeted therapy." (PMID 25992771, 2015). "Other mechanisms, including the involvement of Anexelekto- (Axl-) kinase and a number of miRNAs in the AR of lung cancer to TKIs, and several miRNAs have been demonstrated to be associated with EGFR mutations in lung cancer." (PMID 26273639, 2015). "PIK3CA mutations were most common in breast cancer, and EGFR mutations were most common in lung cancer." (PMID 26015395, 2015). "In this review, we not only introduce the biology and clinical implementations of ctDNA but also include the updating information of recent advancement of techniques for detecting EGFR mutation using ctDNA in lung cancer." (PMID 26448936, 2015). "The identification of somatic mutations within the epidermal growth factor receptor (EGFR) kinase domain helped our understanding of the biology of lung cancer harboring EGFR mutations." (PMID 26515464, 2015). "Even though these small molecular inhibitors are very effective for a subgroup of patients including those with EGFR active mutations, currently its outcome is quite limited for the majority of lung cancer patients." (PMID 26593208, 2015). "The distinctive biomarkers in lung cancer are mutations in the epidermal growth factor receptor (EGFR) or gain-of-function translocations and inversions involving the anaplastic lymphoma receptor tyrosine kinase (ALK)." (PMID 26156018, 2015).
lung cancer (continued). "Postoperative use of angiogenesis drugs EGFR-TKI application were high risk factors for VTE in lung cancer patients." (PMID 26380084, 2015). "While considerable groundbreaking cancer research related to EGFR and its mutations is based on research in lung cancer patients, breast cancer is also known to be strongly associated with EGFR stimulated cell growth." (PMID 26267891, 2015). "The advances in targeted therapies for lung cancer are based on the evaluation of specific gene mutations especially the epidermal growth factor receptor (EGFR)." (PMID 26448936, 2015). "Afatinib, a TKI with activity against ERBB family members is approved for EGFR mutation positive adenocarcinoma and has shown clinical activity in lung cancer patients harboring a HER2 mutation even after failure of other EGFR- or HER2-targeting therapies." (PMID 26018876, 2015). "Because proliferation and survival of lung cancers with EGFR mutation solely depend on aberrant signalling from the mutated EGFR, these tumours often show dramatic responses to EGFR tyrosine kinase inhibitors (TKIs)." (PMID 26400668, 2015). "Second-generation TKIs such as dacomitinib or afatinib that covalently bind to EGFR have been developed, and afatinib has recently obtained marketing approval for first-line treatment of lung cancer patients with common activating EGFR mutations." (PMID 25853020, 2015). "The EGFR P848L mutation we identified is situated close to the L858R mutation, a well-known target in nonsmall cell lung cancer." (PMID 26294908, 2015). "In this study, using PC3 (prostate cancer) and A549 (lung cancer) cells, we explored the mechanism underlying EGFR's ligand-independent activation." (PMID 26378037, 2015). "Dysregulation of EGFR signaling as a consequence of overexpression, amplification, and mutation of the EGFR gene occurs frequently in several types of epithelial cancers, such as lung cancer and colon cancer." (PMID 26064956, 2015). "The most specific predictive marker in NSCLC for TKI response is EGFR mutation in the tyrosine kinase domain, which has been reported in 3–32% of the lung carcinomas." (PMID 26436086, 2015). "Their work associated EGFR signal transactivation with increased cell proliferation in human lung carcinoma in response to cigarette smoking." (PMID 26462152, 2015). "Other molecular events, such as MET proto-oncogene amplifications, have been associated with resistance to EGFR inhibitors in 20% of lung cancers independently of EGFR mutations." (PMID 25036042, 2014). "In EGFR mutant or KRAS mutant lung cancer models, tumor regression associated with apoptosis was also observed only when the PI3K/AKT pathway and MEK/MAPK pathway were simultaneously blocked." (PMID 24337632, 2014). "Nearly 85 % of lung-cancer-specific EGFR mutations comprise a leucine-to-arginine substitution at position 858 (21L858R) and a deletion mutation in exon 19 that affects the conserved sequence LREA (19del)." (PMID 24908327, 2014). "We have also reported that loss of PTEN expression and loss of activating EGFR gene allele results in acquisition of resistance to EGFR-TKIs in lung cancer cells harboring activated EGFR mutations." (PMID 25115383, 2014). "In lung cancer, EGFR response is tightly correlated with activating EGFR mutations, while resistance in colon cancer is mediated by downstream KRAS mutations." (PMID 25428177, 2014). "In this study, we described a novel association between gefitinib, one of the EGFR-TKIs, and EGFR endocytosis in the treatment of lung cancer with wtEGFR using in vitro and in vivo models." (PMID 24658031, 2014). "Overexpression of EGFR is responsible for causing a number of cancers, including lung cancer as it activates various downstream signaling pathways." (PMID 24992720, 2014). "We first used genomic DNA sequencing to examine for the presence of mutations in the EGFR gene in PC-3 cells that were reported previously to be harbored frequently by lung cancer cells." (PMID 24971999, 2014).
lung cancer (continued). "In conclusion, the current study reports a rare case of lung cancer harboring an L858R point mutation of exon 21 and a compound T790M EGFR substitution mutation following treatment with gefitinib." (PMID 25120654, 2014). "Past report suggested the impact of age on EGFR mutation, and concluded that age was associated with EGFR mutation in lung cancer." (PMID 25152277, 2014). "Rab25 knockdown caused the changed EGFR endocytosis and reverted the gefitinib response in gefitinib-sensitive lung cancer with wtEGFR in vitro and in vivo." (PMID 24658031, 2014). "One of the most intriguing recent discoveries in the field of lung cancer research is the identification of new driver mutations in lung adenocarcinomas, such as EGFR mutations and ALK fusion." (PMID 24926563, 2014). "The EGFR mutation has a higher instance than other driver mutations in lung cancer and is sensitive to the EGFR tyrosine kinase inhibitor." (PMID 25490772, 2014). "Several studies have identified certain mutation of susceptible genes to lung cancer, including epidermal growth factor receptor (EGFR) gene and nucleotide excision repair genes." (PMID 25520938, 2014). "Our study firstly demonstrated that EGFR down-regulation caused by CX-4945 enhanced the efficacy of EGFR-TKI on EGFR-mutant lung cancer cells with T790M-mediated resistance." (PMID 25486409, 2014). "Amongst patients with metastatic EGFR mutation positive lung cancer, the patients with brain metastases have a worse outcome as compared to those without brain metastasis at the time of diagnosis." (PMID 25548673, 2014). "Based on previous reports and our findings, we attempted to identify other EGFR-related cellular mechanisms in lung cancer with wtEGFR that were associated with cell survival and the gefitinib response independently of its TK activity." (PMID 24658031, 2014). "Paclitaxel followed by gefitinib was regarded as an effective treatment combination for NSCLC cell lines harboring EGFR mutations, while schedule-dependent synergistic effect was seen in the combinations of gefitinib and irinotecan in lung cancer cell lines." (PMID 24884778, 2014). "It is essential for EGFR mutation detection for patients with advanced lung cancer to targeted therapy." (PMID 24743427, 2014). "The aim of this study was to investigate the clinical importance of EGFR mutations in exons 19 and 21 of lung cancer patients and to compare the outcomes of these patients." (PMID 25404271, 2014). "As expected, the tumors expressing the NTS/NTRS1 complex are responsive to erlotinib, an EGFR inhibitor given to patients with lung cancer bearing EGFR mutations." (PMID 25249545, 2014). "The spectrum of lung cancer-derived EGFR mutations can induce oncogenic transformation by leading to constitutive kinase activity of EGFR and confer markedly different degrees of sensitivity to EGFR inhibitors." (PMID 24817905, 2014). "Both lung cancers with EGFR mutations or ALK translocations are characterized by negative or light smoking history." (PMID 24926563, 2014). "The feasibility of monitoring epidermal growth factor receptor (EGFR) mutations in plasma DNA from patients with advanced non–small cell lung cancer (NSCLC) during treatment with erlotinib and its relation to disease progression was investigated." (PMID 25103305, 2014). "The increased response rates to EGFR inhibitors in certain lung cancers with EGFR tyrosine kinase domain mutations are reported with acquired resistance within one year." (PMID 25198391, 2014). "In vitro studies showed that exposing EGFR-mutant lung cancer cell lines to a mutagen and culturing them in the presence of an EGFR-TKI, the resistant clones with the T790M mutation maintained a persistent phosphorylation." (PMID 25505694, 2014). "The two most commonly mutated oncogenes in lung cancer encode the epidermal growth factor receptor (EGFR) and K-Ras." (PMID 25028095, 2014).
lung cancer (continued). "In lung cancer, EGFR overexpression is associated with cancer proliferation and downregulated EGFR causes cell growth inhibition in CL1-5 cells." (PMID 24816813, 2014). "Consistent with the in vitro data, both CML and EGFR-driven lung cancer patients carrying the polymorphism experienced inferior responses to treatment with tyrosine kinase inhibitors." (PMID 25090024, 2014). "While most oncogenic driver mutations are mutually exclusive in context of lung cancer, the co-existence of EGFR mutations with other oncogenic alterations, including class A phosphoinositide 3-kinase (PI3KCA), have been reported." (PMID 25101246, 2014). "Women also tend to have molecularly distinct lung cancers (higher prevalence of epidermal growth factor receptor mutations) and have a better prognosis." (PMID 24919547, 2014). "L861Q is a frequently observed mutation in EGFR in lung cancer and this mutation is known to activate EGFR; however, the functional impact of the rare L861R is not well understood." (PMID 24743239, 2014). "HGF (hepatocyte growth factor)/MET signaling pathway is associated with acquired resistance to EGFR inhibitors in EGFR mutant non–small cell lung cancers." (PMID 25221930, 2014). "This is analogous to the EGFR T790M mutation in the ATP biding pocket of the EGFR, which is the most common mechanism of resistance in EGFR-mutated lung cancer." (PMID 25101240, 2014). "In complementary, Dr. Carbone’s group found that treatment of EGFR-mutated lung cancer cell lines with erlotinib enriched the ALDH+ stem-like cells with stem-like cell potential through EGFR-dependent activation of Notch3." (PMID 25477004, 2014). "In this study, we show that it is feasible to detect EGFR mutations in plasma from patients with advanced lung cancer." (PMID 24773774, 2014). "In summary, this study provided the first demonstration that DDX3X induced loss of EGFR signal addiction resulting in resistance to EGFR-TKI, accompanied by CSC-like properties and occurrence of the EMT in lung cancer cells harboring EGFR-activating mutation." (PMID 25343452, 2014). "For example, PI3K is activated by EGFR in lung cancers harboring somatic activating mutations in EGFR, and by human epidermal growth factor receptor 2 (HER2) in breast cancers with HER2 amplification." (PMID 25505372, 2014). "Several driver mutations have been identified in lung cancer, such as epidermal growth factor receptor (EGFR) and K-ras mutations and anaplastic lymphoma kinase (ALK) rearrangement." (PMID 24885886, 2014). "Studies have shown that EGFR mutations are associated with gefitinib effectiveness, and EGFR gene mutation detection is a method to predict the outcome of lung cancer patients treated with gefitinib." (PMID 24602316, 2014). "Nearly 85 % of lung-cancer-specific epidermal growth factor receptor (EGFR) sensitive mutations comprise a substitution at position 858 (21L858R) and deletion mutants in exon 19 (19del)." (PMID 24908327, 2014). "In this study, we investigated the activity of CX-4945, a selective and potent CX-2 inhibitor, on EGFR-mutant lung cancer cells with T790M mutation leading to resistance to EGFR-TKIs." (PMID 25486409, 2014). "The backbone of cytotoxic treatment of non-EGFR mutated lung cancers as well as mesothelioma includes platinum derivatives cisplatin and carboplatin." (PMID 25325012, 2014). "T790M is a gatekeeper mutation of EGFR, which appears in half of lung cancer patients treated with EGFR-TKI." (PMID 25462870, 2014). "These biomarkers predict response to these molecular targeting agents and testing for these markers is recommended in lung cancer patients, enabling personalized medicine for patients harboring EGFR mutations or ALK gene rearrangements." (PMID 24885886, 2014). "We sought to develop a sensitive and specific assay to detect mutations in the EGFR gene in CTC from lung cancer patients." (PMID 24465542, 2014).
lung cancer (continued). "The Iressa Survival Evaluation in Lung Cancer (ISEL) phase III study was similar to the NCIC BR.21 trial design as it compared an EGFR TKI to placebo in EGFR mutation-unselected NSCLC patients in the second and third line setting." (PMID 25309870, 2014). "Lung cancer patients with mutations in the epidermal growth factor receptor (EGFR) are primary candidates for EGFR-targeted therapy." (PMID 24773774, 2014). "For example, the discovery of epidermal growth factor receptor (EGFR) mutations in lung cancer was prompted by the clinical observation that a subset of patients exhibited a major response when administered tyrosine kinase inhibitors in clinical trials." (PMID 25198155, 2014). "Past experience with the use of TKIs in chronic myelogenous leukemia as well as EGFR-mutated lung cancer teaches us that most common mechanisms of resistance to this class of medications are secondary mutations in the TK domains." (PMID 25101240, 2014). "Compared to the lung cancer patients with EGFR exon 21 mutations, the patients with EGFR exon 19 mutations were younger, and their primary tumors were more likely to occur in the right lung." (PMID 25404271, 2014). "Multiple EGFR mutations in lung cancer have previously been observed in tumors tissues by ultra deep sequencing as well as in circulating tumor cells." (PMID 25137181, 2014). "Data for PFS of EGFR mutation-positive (EGFR M+) lung cancer were available from 3 trials and data for OS of EGFR M+ lung cancer were available from 2 trials." (PMID 25029199, 2014). "Although common among lung cancer patients of Asian descent, sensitizing EGFR mutations are relatively uncommon in North American and European NSCLC populations with a prevalence of ~15% in patients with advanced non-squamous histology." (PMID 25101246, 2014). "Lung cancer therapy has changed enormously over the last years thanks to the discovery of specific mutations (EGFR, KRAS, ALK, ROS1), and thus the introduction of targeted therapies." (PMID 25593996, 2014). "In our sample set 50% of EGFR-associated lung cancers metastasized to local regions, 27.3% to lymphs and 46.2% of cancers metastasized to distant organs in our sample set." (PMID 24760004, 2014). "In analogous settings, secondary mutations, such as KIT exon 17 mutations in imatinib-resistant GIST and EGFR T790M in EGFR-mutated lung cancers are common mechanisms of resistance." (PMID 25238247, 2014). "Other types of cancers like lung cancer often bear mutations within the EGFR gene, and colon cancer often exhibits mutations in the k-ras gene, which acts downstream of EGFR." (PMID 24621372, 2014). "EGFR (Epidermal Growth Factor Receptor)-targeted therapy has been used in the treatment of LC (lung cancer), mainly caused by the carcinogens in cigarette smoke, with variable success." (PMID 25222473, 2014). "To further investigate Sox9 overexpression in lung ADC, we queried data with annotated mutational information and analyzed Sox9 expression within lung cancer genetic subgroups, including EGFR and KRAS mutations." (PMID 25004243, 2014). "For this reason, in addition to mutational analysis immunohistochemistry (IHC) of EGFR in lung cancer has been discussed for the decision making of according therapeutic strategies." (PMID 25227424, 2014). "Since the recognition of epidermal growth factor receptor (EGFR) as a therapeutic target, EGFR tyrosine kinase inhibitors (TKIs) have been used in lung cancer patients with EGFR mutations, which has been a major breakthrough for lung cancer treatment.." (PMID 24410791, 2014). "In lung cancer the prevalence of EGFR mutations varies from 10% in Caucasians to more than 40% in Asian populations." (PMID 24885034, 2014). "It has been demonstrated that the majority of patients with lung cancer that are responsive to EGFR-TKIs harbor activating mutations in the TK domain of EGFR." (PMID 25120654, 2014).